RN7SKP273 (RN7SK pseudogene 273)
Gene: Miscellaneous RNA gene on chromosome 11 (111,683,111 to 111,683,424, forward strand). Ensembl gene ENSG00000223324.
Homologues: Orthologues: chimpanzee 7SK (99% identical), guinea pig 7SK (53% identical). Paralogues in human: RN7SKP255 (76% identical), RN7SKP176 (76% identical), RN7SKP204 (74% identical), RN7SKP180 (74% identical), RN7SKP124 (73% identical), RN7SKP44 (73% identical), RN7SKP78 (73% identical), RN7SKP79 (73% identical), RN7SKP203 (73% identical), RN7SKP50 (73% identical), RN7SKP71 (73% identical), RN7SKP9 (73% identical), and 284 more.